OR10H3 (olfactory receptor family 10 subfamily H member 3)
Description:
Odorant receptor.
Tractability: Antibody: UniProt places it where antibodies can reach, with medium confidence; UniProt predicts a signal peptide or a membrane-spanning region; its Gene Ontology location is reachable by antibodies, with medium confidence.
Gene: Protein-coding gene on chromosome 19 (15,737,985 to 15,742,343, forward strand). Ensembl gene ENSG00000171936.
Subcellular location: Cell membrane
Pathways (Reactome):
Sensory Perception: Expression and translocation of olfactory receptors
Gene Ontology:
Molecular function: olfactory receptor activity; G protein-coupled receptor activity
Biological process: detection of chemical stimulus involved in sensory perception of smell; G protein-coupled receptor signaling pathway
Cellular component: plasma membrane; membrane
Genetic constraint (gnomAD): Loss-of-function variants: 14 observed, 10.85 expected, observed/expected ratio (o/e) 1.29, 90% interval 0.84 to 1.85. The upper end of that interval is the gene's LOEUF score, 1.85, which puts it in group 6 of 6, group 1 being the genes least tolerant of losing a copy. Missense variants: 397 observed, 397.86 expected, observed/expected ratio (o/e) 1, 90% interval 0.92 to 1.08. Synonymous variants: 147 observed, 145.84 expected, observed/expected ratio (o/e) 1.01, 90% interval 0.88 to 1.16.
Homologues: Orthologues: chimpanzee OR10H3 (96% identical), dog OR10H4C (81% identical), dog OR10H1E (79% identical), mouse Or10h28 (77% identical). Paralogues in human: OR10H4 (90% identical), OR6B3 (41% identical), OR6B2 (40% identical), OR8B4 (40% identical), OR8U3 (40% identical), OR10V1 (39% identical), OR8D4 (39% identical), OR8H1 (39% identical), OR8H2 (39% identical), OR9I1 (39% identical), OR10Q1 (38% identical), OR5D18 (38% identical), and 84 more.